INS (insulin)
Diseases named in the same sentence as INS in open-access papers (continued):
Sharing a sentence is not in itself a finding about the gene and the disease.
Obesity (continued). "Ghrelin is a peptide hormone secreted from enteroendocrine cells of the gastrointestinal tract that has diverse biological functions, including appetite and obesity regulation, inhibition of insulin secretion, and stimulation of growth hormone release." (PMID 35409338, 2022). "Changes in SORBS3 expression after surgery were correlated with obesity measures and fasting insulin levels." (PMID 36397166, 2022). "This combined with the upregulation of RETN inhibits insulin action and presents a possible link between BPA exposure causing obesity and insulin resistance." (PMID 35199272, 2022). "This species has recently been shown to prevent obesity and the evolution of hypertension and heart failure in hypertensive mice, to improve insulin sensitivity in mice, and to decrease the severity of allergic airway disease." (PMID 36558387, 2022). "Ghrelin levels are known to inversely correlate with measures of obesity, including BMI, percent body fat, and circulating levels of both insulin and leptin." (PMID 35454071, 2022). "Participants with overweight/obesity taking part in the cinnamon/capsicum study were significantly older, had higher fasting plasma glucose and were more insulin resistant than those taking part in the NC/HC meal- challenge study." (PMID 36296989, 2022). "In contrast, genetic ablation of STAT4 resulted in reduced inflammation in AT and improved insulin sensitivity in HFD-induced obesity." (PMID 36555392, 2022). "TZDs inhibit the Cdk5-mediated Ser273 phosphorylation of PPARγ in adipose tissue, which in turn, down-regulate expression of genes involved in obesity, including adipsin, a fat-cell-selective gene, and adiponectin, an insulin-sensitizing adipokine." (PMID 35769384, 2022). "With obesity, there is altered levels of catecholamines, glucose, and cytokines such as IFNγ, but also hormones like leptin and insulin." (PMID 36713396, 2022). "In the clinical treatment of patients with obesity who is taking insulin alone, AM has been demonstrated to improve triglyceride metabolism in the body." (PMID 35907080, 2022). "n-3 and n-6 PUFA help to improve long-term glycemic control and insulin secretion capacity and reduce cardiovascular metabolic syndrome and obesity rates in the population." (PMID 36304417, 2022). "Obesity- or aging-induced adipocyte dysfunction triggers infiltration of inflammatory M1 macrophages and reduces the population of insulin-sensitizing M2 macrophages." (PMID 35216174, 2022). "As emerged from studies performed in both human and animal models of obesity and neurodegenerative diseases, an impairment of BVR-A occurs before IRS1 inhibition and is associated with a reduced insulin signaling activation." (PMID 35628384, 2022). "In the present study, the increase in insulin concentration in obesity-induced mice was possibly related to the increase in peripheral abdominal fat due to HFD consumption." (PMID 36193302, 2022). "The calculated HOMA/IR index showed a significant reduction in the HFD-PomE group compared to the HFD group (p-value 0.047), although without recovering the levels of the ND group, indicating that PomE improves insulin sensitivity after HFD-induced obesity." (PMID 36142372, 2022). "A cross-sectional study which enrolled 115 postmenopausal women showed that women with high lignans intake had better metabolic status, including higher insulin sensitivity and lower obesity indexes." (PMID 35399831, 2022). "The aim of this study was to assess association between OPG and BNP concentrations in a young healthy population, their relation to insulin sensitivity and obesity and their regulation by hyperinsulinemia and serum free fatty acids (FFA) elevation." (PMID 35215487, 2022). "In women with normal weight and obesity, central insulin action decreased palatable food intake (i.e., cookies) in the postprandial state." (PMID 35715625, 2022).
Obesity (continued). "In fact, obesity alters insulin signaling pathways and appears to be responsible for the neuroinflammatory process and cognitive impairment." (PMID 35458168, 2022). "In the mouse model of high-fat diet-induced obesity, we found that Trem1 suppression limited weight gain, insulin resistance and inflammation in white adipose tissue and liver." (PMID 36699032, 2022). "Animal models of complete DPP4 silencing demonstrate that the DPP4 contributes to the development of obesity and insulin resistance in the condition of chronic caloric excess and positive energy balance." (PMID 36140405, 2022). "In 17 middle-aged subjects with obesity and normal glucose tolerance who underwent the procedure of the hyperinsulinemic-euglycemic clamp with continuous insulin infusion, the expression of core clock genes PER2 and PER3 was increased." (PMID 36432465, 2022). "The top 3 keywords with the most occurrences were “obesity,” “adipose tissue,” and “insulin resistance”." (PMID 35687773, 2022). "T2DM is characterized by chronic hyperglycemia caused by a combination of insulin resistance (IR) and an inadequate compensatory insulin secretion, and usually occurs in subjects with obesity." (PMID 36676944, 2022). "Maternal fasting cholesterol and insulin were significantly elevated in women with obesity, while there was a trend for triglycerides to be higher (P = 0.056)." (PMID 36371454, 2022). "Similar to AT, skeletal muscles also show increased macrophage infiltration, inflammation, impaired insulin signaling and systemic glucose tolerance in conditions of obesity." (PMID 35909571, 2022). "We concluded that before the onset of obesity, short-term exposure to high-nutrition diets already blunted central responses to insulin, altered gut microbiome composition, and activated inflammatory mediators." (PMID 35873818, 2022). "Ceramides and oxidative stress, which are elevated in obesity and insulin resistance, also negatively affect insulin signaling and GLUT4 translocation in skeletal muscle cells." (PMID 35683979, 2022). "Adiponectin with insulin-sensitization, antiangiogenic, anti-inflammatory, and anti-neoplastic properties is reduced in obesity." (PMID 34751020, 2022). "We have previously shown that acute infusions of lipid and insulin into normal weight women recapitulates the obesity phenotype of decreased basal and GnRH-stimulated LH and FSH secretion, which we have termed ‘Reprometabolic Syndrome’." (PMID 35544473, 2022). "On the other hand, impaired proinsulin processing mediated the obesity phenotype in Pcsk1fl/flPdx-CreERT mice, and insulin replacement by implanting subcutaneous insulin pellets prevented hyperphagia." (PMID 35963866, 2022). "The reasons for the younger age of onset in relation to obesity, beta cell function and insulin sensitivity are under-explored." (PMID 35247066, 2022). "Previous studies have correlated the glucose, myo-inositol, fatty acids and amino acids levels changes to increased insulin levels in children and adolescents with obesity, as well as PCOS in girls." (PMID 36239863, 2022). "RBP4 is a proinflammatory adipokine, and its circulating levels are increased in insulin-resistant states, during AT expansion and in obese humans and mouse models of obesity." (PMID 36499659, 2022). "The PPARGC1A gene rs8192678 polymorphism has been previously related to the development of obesity, biochemical parameters such as glucose, insulin, triglycerides and inflammatory markers, resting energy expenditure, and physical fitness level." (PMID 35936915, 2022). "AMF reduces HFD-induced obesity and hyperglycemia by regulating lipogenesis and insulin signaling and streptozotocin-induced hyperglycemia by activating the PI3K/Akt signaling pathway in mice." (PMID 35454963, 2022). "Patients with obesity and T2D display “metabolic inflexibility” manifested by impaired insulin-stimulated skeletal muscle glucose oxidation." (PMID 35440636, 2022).
Obesity (continued). "CA3 expression levels are affected by several factors, such as obesity (fat accumulation), insulin, and adipokines." (PMID 35108454, 2022). "A large number of literature studies have been well documented that aerobic exercise can ameliorate obesity, modify the lipid profile, and improve insulin sensitivity." (PMID 35782940, 2022). "Meanwhile, another study in adults showed that the insulin concentration in participants with obesity was significantly higher than that in people with normal body weight." (PMID 36235626, 2022). "Previous studies have reported that increased HIF3α promoter methylation is associated with obesity and higher plasma glucose levels and waist-hip ratio and adipose tissue dysfunction, T2DM and lower insulin sensitivity." (PMID 36992770, 2022). "Many studies have indicated beneficial effects of SCFAs, specifically, acetate, propionate, and butyrate, on energy homeostasis and metabolism, and their crucial role in preventing HFD-induced obesity and improving insulin sensitivity." (PMID 35565729, 2022). "Obesity has a direct effect on certain hormone levels, such as insulin, oestrogen, and insulin-like growth factor-1, which produce a favourable environment for carcinogenesis." (PMID 36517625, 2022). "Benzoic acid is involved in the composition of the compound Mn (III) tetrakis (4-benzoic acid) porphyrin chloride (MnTBAP), which reduces obesity by reducing adipocyte hypertrophy and adipogenesis and regulating energy balance and improves insulin function." (PMID 36733447, 2022). "In this study, we provide compelling evidence that miR-34a, whose expression is increased in adipose tissue and adipocyte during obesity, contributes to the alteration in insulin signaling and action in adipocytes." (PMID 36010657, 2022). "Yet to date the literature offers little insight into brain insulin expression in diet-induced obesity." (PMID 36244663, 2022). "It improves vital obesity parameters and insulin sensitivity, and rescues glucose homeostasis in HFD mice." (PMID 35054790, 2022). "Obesity-associated BBS is paradoxically by related to lower susceptibility to develop T2D early in life (2-6% prevalence in childhood), and higher insulin sensitivity and glucose usage." (PMID 35832432, 2022). "IL-22-Fc treatment restores liver insulin sensitivity, decreased hepatic triglyceride and cholesterol levels, and ameliorated liver steatosis in diet-induce obesity and db/db mice." (PMID 35574038, 2022). "If so, further investigations into the role of the association between circulating MCP-1 concentrations in relation to obesity related low-grade inflammation and insulin sensitivity in cats should be performed." (PMID 36064726, 2022). "In contrast, global 11β-HSD1 knockout mice showed improved glucose tolerance, insulin sensitivity, and resistance to obesity when fed a high fat diet." (PMID 36131216, 2022). "Our overarching aim was to identify novel insulin-expressing cell populations outside of the hypothalamus, and determine their physiological role in health and during diet-induced obesity challenge in mice." (PMID 36244663, 2022). "to explain the increase in insulin sensitivity and resistance to high-fat diet-induced obesity in mice with muscle OGT KO." (PMID 36058931, 2022). "Long-term glucose management of PTDM frequently requires insulin over time, particularly in those with the greatest obesity." (PMID 35501824, 2022). "Mice deficient in bid (bid−/−) were resistant to high‐fat diet (HFD)–induced obesity, hepatic steatosis, and dyslipidemia with an increased insulin sensitivity." (PMID 36382356, 2022). "Obesity modifies carbohydrate (CHO) metabolism by insulin-dependent tissues,particularly skeletal muscle." (PMID 35857997, 2022). "The CSF/plasma insulin ratio is reduced in obesity, and age-dependent changes in the ratio are also observed in the elderly." (PMID 35052794, 2022).
Obesity (continued). "As obesity was induced in the control group, insulin and HOMA-IR were significantly elevated, but the PUE group showed no significant advantage in both values." (PMID 35052852, 2022). "Achieving healthy levels of Akkermansia has been identified as a potential probiotic target to decrease inflammation, reduce obesity, and improve insulin sensitivity." (PMID 36005503, 2022). "The current study aimed to compare the performance of SPISE as an estimation of hepatic impaired insulin sensitivity in children and adolescents with obesity." (PMID 35185803, 2022). "Genus Peptococcus ferments amino acids to produce polyamines, which improve glucose homeostasis and insulin sensitivity and ameliorate obesity in mouse models." (PMID 35865826, 2022). "These phenotypes were consistent with those of adipocyte‐specific Atg7 KO mice, where loss of autophagic function decreases WAT mass, enhances insulin sensitivity and protects the mice from HFD‐induced obesity." (PMID 35184387, 2022). "The insulin utilization rate was different among the three groups; the overweight and obesity group showed the highest insulin utilization rates." (PMID 36960096, 2022). "As obesity is closely correlated with hyperglycemia and hyperinsulinemia, the concentrations of fasting blood glucose and fasting serum insulin were detected." (PMID 36505236, 2022). "ACACB knockout mice have been shown to be protected from HFD-induced obesity and T2D through increased FA and glucose oxidation activity and increased lipolysis, thus promoting the maintenance of insulin sensitivity." (PMID 35159548, 2022). "Turicibacter and Romboutsia were positively correlated with indicators of obesity-like TG, TC, and insulin." (PMID 35682591, 2022). "Obesity subjects reveal increased peripheral lipolysis due to insulin resistance, which in turn generates circulating fatty acids." (PMID 36077467, 2022). "It is well established that people with obesity have higher basal and postprandial plasma insulin concentrations than lean people." (PMID 35054781, 2022). "Nevertheless, as obesity progresses, preadipocyte differentiation becomes dysfunctional, leading to reduced insulin signalling, glucose uptake and adiponectin release by mature adipocytes." (PMID 35886846, 2022). "Heterozygous BDNF knockout mice had reduced BDNF expression which led to age-dependent obesity and an insulin-resistant phenotype, and were characterised by elevated circulating levels of insulin, leptin and glucose." (PMID 36008755, 2022). "We found that pregestational BMI was significantly associated with an earlier diagnosis of GDM and increased requirement of glucose lowering medication, with mothers with obesity needing the highest amount of insulin units per day." (PMID 35663318, 2022). "This serves as a potential mechanism by which obesity, via pro-inflammatory cytokine upregulation, can reduce insulin sensitivity and glucose uptake in peripheral tissues such as adipose." (PMID 35784876, 2022). "Among the four phenotypes of PCOS, classic PCOS patients demonstrated higher insulin levels, greater rates of IR, higher body mass index (BMI), and a higher incidence of obesity, whereas patients with "ovulatory PCOS" had milder clinical and endocrine changes." (PMID 35719759, 2022). "Epidemiological studies revealed an association between increased levels of insulin and cancer risk, including breast, pancreatic, and endometrial cancers, indicating that hyperinsulinemia may be a key risk factor for cancer in patients with obesity and diabetes." (PMID 35563777, 2022). "Loss of function of Fam83a in WAT inhibited fat accumulation and resisted diet-induced obesity while improving insulin sensitivity." (PMID 35931121, 2022). "The prevalence of depression is known to be increased in the setting of obesity, a condition that promotes inflammation as well as resistance to insulin and leptin." (PMID 35911213, 2022).
Obesity (continued). "Here we investigated the role of microglial insulin signaling during health and obesity on the anorexigenic proopiomelanocortin (POMC) neurons, as they have been previously shown to be highly sensitive to a chronic hypercaloric environment." (PMID 35328354, 2022). "Western style diet (WD, containing HFD plus high sucrose) induced paternal obesity has also been shown to increase bodyweight, impair glucose metabolism and insulin sensitivity in male and female mice offspring." (PMID 35022547, 2022). "Injury of hypothalamus, enhanced by obesity, disrupts the effects of several metabolic hormones (ghrelin, insulin, leptin, glucagon-like peptide 1 (GLP-1)), which are key regulators of appetite." (PMID 35887234, 2022). "Reduced insulin clearance has also been increasingly identified in young/adolescent subjects with obesity and NAFLD." (PMID 36009446, 2022). "AEA has been suggested to play a role in regulating appetite and energy expenditure and plasma AEA was elevated in obesity and suppressed with insulin infusion, consistent with our findings." (PMID 36557310, 2022). "Although participants of both clinical studies were males with overweight or obesity, those from the cinnamon/capsicum study were older and more insulin resistant." (PMID 36296989, 2022). "The prevalence of obesity in patients with T1DM is also rising and is associated with insulin pump therapy, early onset, puberty, female sex, and low levels of physical activity." (PMID 36578961, 2022). "In the per-protocol analysis, all 3 groups had similar baseline profiles except for higher frequency of general obesity and lower insulin use in the usual care group (eTable 9 in Supplement 2)." (PMID 35333363, 2022). "Adolescents with obesity, compared to normal-weight peers, had elevated plasma lipid, insulin c-peptide, and hs-CRP levels, the latter increasing exponentially with increasing adiposity." (PMID 35846851, 2022). "A possible explanation for this disagreement is the smaller contribution of MUH to OLF than of obesity in our cohort, because of low levels of systemic inflammation and insulin resistance, which link metabolic derangement and lung function impairment." (PMID 35417494, 2022). "After challenge, major differences were observed at latter time points in the levels of insulin, glucose, and leptin, indicating that the regulation of endocrine factors and inflammatory events are largely dysregulated in obesity." (PMID 35406000, 2022). "DGAT1 knockout mice have been shown to develop resistance to diet-induced obesity and have improved insulin sensitivity due to reductions in the expression levels of genes involved in lipid uptake and oxidation, thus preventing lipotoxicity." (PMID 35159548, 2022). "In brain, obesity leads to an inflammatory process that impairs both insulin and leptin signaling in the hypothalamus, exacerbating obesity (Jais and Brüning, 2017)." (PMID 35112705, 2022). "It has been previously reported that female mice have greater insulin sensitivity in diet-induced obesity models, and this has also been shown in women." (PMID 36687716, 2022). "In parallel with reduced diet-induced obesity, mice devoid of Ager globally or in adipocytes displayed reduced insulin resistance." (PMID 35562970, 2022). "As one of the clinical manifestations of PCOS, obesity is also related to poor pregnancy outcomes in women with PCOS and is usually associated with high circulating insulin levels, which in turn increase ovarian androgen production." (PMID 35733779, 2022). "Our findings contradict the common view that insulin hypersecretion in people with obesity is a compensatory β cell response to insulin resistance." (PMID 34905513, 2022). "According to Hojlund, besides disturbances in oxidation, obesity is accompanied by alterations in the insulin signaling transduction pathway." (PMID 36078293, 2022). "The coexistence of polycystic ovary syndrome and obesity shows a synergistic, unfavorable effect on the insulin." (PMID 36246904, 2022).